TARDBP (TAR DNA binding protein)
Diseases named in the same sentence as TARDBP in open-access papers (continued):
Sharing a sentence is not in itself a finding about the gene and the disease.
amyotrophic lateral sclerosis (continued). "The cause of amyotrophic lateral sclerosis (ALS) is not yet fully understood, but TAR DNA-binding protein (TDP-43) aggregates are considered one of the key pathogenic agents since they are found in 97% of all ALS patients." (PMID 38474412, 2024). "TAR DNA-binding protein 43 (TDP-43) proteinopathy in brain cells is the hallmark of amyotrophic lateral sclerosis (ALS) but its cause remains elusive." (PMID 38755145, 2024). "The aim of this article was to depict in depth the cognitive-behavioral characteristics of a cohort of patients with amyotrophic lateral sclerosis (ALS) carrying TARDBP pathogenetic variants followed by an ALS referral center." (PMID 38261982, 2024). "Although loss of TAR DNA-binding protein 43 kDa (TDP-43) splicing repression is well documented in postmortem tissues of amyotrophic lateral sclerosis (ALS) and frontotemporal dementia (FTD), whether this abnormality occurs during early-stage disease remains unresolved." (PMID 38278991, 2024). "Aggregation of the RNA-binding protein TAR DNA binding protein (TDP-43) is a hallmark of TDP-proteinopathies including amyotrophic lateral sclerosis (ALS) and frontotemporal dementia (FTD)." (PMID 38739752, 2024). "Finally, the use of these selective probes or deconjugases for mATG8–PE revealed that GABARAP subfamily proteins regulate the cellular degradation of amyotrophic lateral sclerosis (ALS)-linked TDP-25 (the 25-kDa C-terminal fragment of TARDBP/TDP-43) protein aggregates during aggrephagy." (PMID 36250672, 2023). "Pathological aggregation of TAR DNA-binding protein 43 (TDP-43) in neurons is a key hallmark of almost all amyotrophic lateral sclerosis (ALS) and approximately half of frontotemporal dementia (FTD) cases." (PMID 36930291, 2023). "Amyotrophic lateral sclerosis (ALS) associated with TAR DNA-binding protein 43 (TDP-43) aggregation has been considered as a lethal and progressive motor neuron disease." (PMID 37101169, 2023). "Mutations in TARDBP caused familial amyotrophic lateral sclerosis (ALS) and frontotemporal dementia (FTD)." (PMID 36052164, 2022). "We therefore examined the localization of TAR DNA-binding protein 43 (TDP-43)—an amyotrophic lateral sclerosis (ALS)-associated protein—because TDP-43 is known to be recruited to SGs in response to neuronal injury." (PMID 36195595, 2022). "TARDBP is a nuclear DNA/RNA-binding protein involved in RNA metabolism, and is a pathological hallmark of amyotrophic lateral sclerosis (ALS)." (PMID 33750298, 2021). "Mislocalization of the TAR DNA-binding protein 43 (TDP-43; encoded by TARDBP) from the nucleus to the cytoplasm is a common feature of neurodegenerative conditions such as amyotrophic lateral sclerosis (ALS) and frontotemporal lobar degeneration (FTLD)." (PMID 33408125, 2021). "Amyotrophic lateral sclerosis (ALS) shows progressive loss of motor neurons with the accumulation of ubiquitinated TAR DNA-binding protein-43 (TDP-43)." (PMID 34635103, 2021). "The human endogenous retrovirus-K (HERV-K) and TAR DNA-binding protein 43 (TDP-43) have been associated with the pathophysiology of amyotrophic lateral sclerosis (ALS)." (PMID 34835107, 2021). "Protein aggregation is also a feature of amyotrophic lateral sclerosis (ALS) and frontotemporal lobar dementia (FTD); the 43-kDa TAR DNA-binding protein (TDP-43) aggregates in ALS and the microtubule-associated protein tau aggregates in FTD and AD." (PMID 34485280, 2021). "TAR DNA-binding protein 43 (TDP-43) is most notably associated with amyotrophic lateral sclerosis (ALS), and over 50 mutations in the TARDP gene coding for TDP-43 have been found to cause ALS." (PMID 32264976, 2020). "Pathological forms of TAR DNA-binding protein 43 (TDP-43) are present in motor neurons of almost all amyotrophic lateral sclerosis (ALS) patients, and mutations in TDP-43 are also present in ALS." (PMID 32907630, 2020).
amyotrophic lateral sclerosis (continued). "Cytoplasmic inclusion of TAR DNA-binding protein 43 (TDP-43) is a pathological hallmark of amyotrophic lateral sclerosis (ALS) and a subtype of frontotemporal lobar degeneration (FTLD)." (PMID 33097688, 2020). "Intracellular mislocalization of TAR DNA-binding protein 43 (TDP-43), a nuclear DNA/RNA-binding protein involved in RNA metabolism, is a pathological hallmark of amyotrophic lateral sclerosis (ALS)." (PMID 31345270, 2019). "It has been shown that mutation in FUS and TARDBP are associated with amyotrophic lateral sclerosis(ALS), a motor neuron disease by leading to neuronal cell death." (PMID 31017923, 2019). "TDP‐43 (encoded by the gene TARDBP) is an RNA binding protein central to the pathogenesis of amyotrophic lateral sclerosis (ALS)." (PMID 29764981, 2018). "TAR DNA-binding protein (TDP-43) is an amyotrophic lateral sclerosis (ALS)-associated RBP, a marker of neurodegeneration commonly found in inclusions in ALS." (PMID 28529475, 2017). "Mutations in the gene TARDBP, which encodes TAR DNA-binding protein 43 (TDP-43), are a rare cause of familial forms of amyotrophic lateral sclerosis (ALS) and frontotemporal dementia (FTD)." (PMID 28286471, 2017). "Amyotrophic lateral sclerosis (ALS) is a fatal neurodegenerative disease associated with aggregation of TAR DNA-binding protein-43 (TDP-43) in neuronal cells and manifests as motor neuron dysfunction & muscle atrophy." (PMID 28000730, 2016). "TARDBP dysfunction has been linked to neurological disorders, such as amyotrophic lateral sclerosis (ALS), frontotemporal lobar dementia (FTLD) and Alzheimer’s disease (AD)." (PMID 24809979, 2014). "Mutations in TAR DNA-binding protein 43 (TDP-43) are associated with familial forms of amyotrophic lateral sclerosis (ALS), while wild-type TDP-43 is a pathological hallmark of patients with sporadic ALS and frontotemporal lobar degeneration (FTLD)." (PMID 23475610, 2013). "The aggregation of TAR DNA-binding protein (TDP-43) has been shown as a hallmark of amyotrophic lateral sclerosis (ALS) and frontotemporal lobar degeneration (FTLD) since 2006." (PMID 23737961, 2013). "Accumulating evidence suggests that pathogenic TAR DNA-binding protein (TDP)-43 fragments contain a partial RNA-recognition motif domain 2 (RRM2) in amyotrophic lateral sclerosis (ALS)/frontotemporal lobar degeneration." (PMID 23300771, 2012). "The human Tar-DNA binding protein, TDP-43, is associated with amyotrophic lateral sclerosis (ALS) and other neurodegenerative disorders." (PMID 22870402, 2012). "TARDBP mutations have been reported in patients with amyotrophic lateral sclerosis (ALS) in different populations except Chinese." (PMID 20082726, 2010). "Glycation of superoxide dismutase 1 (SOD1) has been shown to modulate the cytosolic levels of phosphorylated TAR DNA-binding protein 43 (TDP-43), a hallmark of amyotrophic lateral sclerosis (ALS) pathology." (PMID 42074053, 2026). "Cytosolic inclusions of aggregated TAR DNA-binding protein 43 (TDP-43) are hallmarks of neurodegenerative disorders such as amyotrophic lateral sclerosis and frontotemporal lobar dementia." (PMID 42171508, 2026). "TAR DNA-binding protein 43 (TDP-43) is of particular interest in the pathogenesis of amyotrophic lateral sclerosis (ALS)." (PMID 40661327, 2025). "Nuclear clearance and cytoplasmic aggregation of TAR DNA-binding protein 43 (TDP-43) are observed in many neurodegenerative disorders, including amyotrophic lateral sclerosis (ALS) and frontotemporal dementia (FTD)." (PMID 40454469, 2025). "TAR DNA-binding protein of 43 kDa (TDP-43) proteinopathies including amyotrophic lateral sclerosis (ALS), frontotemporal dementia (FTD), and Huntington disease (HD) are neurodegenerative disorders characterized by TDP-43 pathology." (PMID 40426231, 2025).
amyotrophic lateral sclerosis (continued). "TAR DNA-binding protein 43 (TDP-43), a predominantly nuclear DNA/RNA-binding protein, forms cytoplasmic aggregates that represent a hallmark pathological feature of amyotrophic lateral sclerosis (ALS)." (PMID 41359111, 2025). "TAR DNA‐binding Protein 43 kilodaltons (TDP‐43) plays a crucial role in the pathophysiology and progression of amyotrophic lateral sclerosis, affecting familial and sporadic cases." (PMID 40960392, 2025). "These disorders include amyloid β (Aβ) for Alzheimer’s disease, superoxide dismutase 1 (SOD1) or Tar DNA binding protein-43 (TDP-43) for amyotrophic lateral sclerosis, and modified α-syn, such as nitrated or phosphorylated α-syn, for Parkinson’s disease." (PMID 40313365, 2025). "Elevated blood endotoxin levels in amyotrophic lateral sclerosis patients correlate with accelerated TAR-DNA binding protein of 43 kDa aggregation and neuropathology." (PMID 40824609, 2025). "In 2006, TAR DNA-binding protein of 43 kDa (TDP-43) was discovered as the major ubiquitinated and aggregated protein in approximately 95% of amyotrophic lateral sclerosis (ALS) cases and 45% of frontotemporal lobar degeneration (FTLD) cases." (PMID 39456026, 2024). "The Drosophila Amyotrophic Lateral Sclerosis (ALS) model expresses mutant forms of genes associated with ALS, such as superoxide dismutase 1 (SOD1) and TAR DNA-binding protein 43 (TDP-43), have contributed to our understanding of ALS pathogenesis." (PMID 39590469, 2024). "The proteins implicated in amyotrophic lateral sclerosis (ALS), including TAR DNA-binding protein 43 (TDP-43), fused in sarcoma (FUS), superoxide dismutase 1 (SOD1), and chromosome 9 open reading frame 72 (C9orf72) repeat peptides, are also related to the DDR." (PMID 39063148, 2024). "Such a mechanism occurs in Amyotrophic Lateral Sclerosis, a progressive NDD in which loss of function by nuclear-to-cytoplasmic mislocalization of TAR DNA binding protein 43 kDa (TDP-43) plays a major causative role." (PMID 37199746, 2023). "The accumulation of TAR DNA-binding protein 43 (TDP-43) underlies a variety of syndromes, being the primary cause of many cases of frontotemporal dementia (FTD) and most cases of amyotrophic lateral sclerosis (ALS)." (PMID 37150879, 2023). "The major proteins involved in neurodegeneration include amyloid beta (Aβ) and tau in Alzheimer’s disease, α-synuclein in Parkinson’s disease, and TAR DNA-binding protein (TDP-43) in amyotrophic lateral sclerosis (ALS)." (PMID 36834792, 2023). "The C9ORF72-linked diseases amyotrophic lateral sclerosis (ALS) and frontotemporal dementia (FTD) are characterized by the nuclear depletion and cytoplasmic accumulation of TAR DNA-binding protein 43 (TDP-43)." (PMID 37466726, 2023). "For example, TAR DNA-binding protein 43 (TDP-43) and fused in sarcoma (FUS), which are associated with amyotrophic lateral sclerosis, are DNA/RNA-binding proteins that contain nuclear localization sequences (NLS)." (PMID 37047616, 2023). "The first disease is amyotrophic lateral sclerosis (ALS), which has been suggested to be mainly caused by a mutation in the nuclear DNA/RNA binding protein called TAR DNA-binding protein 43 (TDP-43)." (PMID 37686127, 2023). "TAR DNA-binding protein 43 (TDP-43) and Fused in Sarcoma/Translocated in Sarcoma (FUS) are ribonucleoproteins associated with pathogenesis of amyotrophic lateral sclerosis (ALS) and frontotemporal lobar degeneration (FTLD)." (PMID 38111057, 2023). "In support of this notion, the toxic fragments of TARDBP/TDP-43 (TAR DNA binding protein) associated with amyotrophic lateral sclerosis (ALS) have been detected in extracellular vesicles containing CASA complex members and their secretion increased upon combined UPS and autophagy blockage." (PMID 36594740, 2023). "In terms of brain pathology, abnormal aggregates of TAR-DNA-binding protein-43 are predominantly present in frontotemporal dementia and amyotrophic lateral sclerosis patients." (PMID 35202463, 2022).
amyotrophic lateral sclerosis (continued). "The pathological hallmark of the majority of amyotrophic lateral sclerosis (ALS) cases is the mislocalization and aggregation of TAR DNA-binding protein 43 (TDP-43), an RNA-binding protein." (PMID 35015250, 2022). "Aggregates of TAR DNA-binding protein (TDP-43) cleavage products are found in subtypes of frontotemporal dementia and amyotrophic lateral sclerosis (ALS)." (PMID 36555634, 2022). "Genetic mutations in TARDBP, C9orf72, MAPT and SOD1 have been used to classify frontotemporal dementia and amyotrophic lateral sclerosis." (PMID 35202463, 2022). "TAR DNA‐binding protein (TDP‐43) is the major aggregating protein in amyotrophic lateral sclerosis (ALS) and frontotemporal dementia (FTD) patients and also forms pathological aggregates in up to 50% of Alzheimer's disease patients." (PMID 35112738, 2022). "For instance, both individuals with frontotemporal lobar degeneration (FTLD) and those with amyotrophic lateral sclerosis have the accumulation of misfolded TAR DNA-binding protein-43 (TDP-43) in their bodies (ALS)." (PMID 36010353, 2022). "Transposable element activation through TAR DNA binding protein 43 (TDP-43)-regulated siRNA-silencing in a frontotemporal region causes dementia and amyotrophic lateral sclerosis (ALS) in Drosophila model, as well as in chick and human cell." (PMID 35887150, 2022). "TDP-43 (TAR DNA-binding protein 43) aggregation and redistribution are recognised as a hallmark of amyotrophic lateral sclerosis and frontotemporal dementia." (PMID 35383280, 2022). "TAR DNA-binding protein 43 kDa (TDP-43), a nuclear protein, plays an important role in the molecular pathogenesis of amyotrophic lateral sclerosis (ALS)." (PMID 36056157, 2022). "TAR DNA binding protein 43 (TDP-43) is closely related to the pathogenesis of amyotrophic lateral sclerosis (ALS) and translocates to stress granules (SGs)." (PMID 36123343, 2022). "In amyotrophic lateral sclerosis (ALS), TAR DNA-binding protein 43 (TDP-43), which is encoded by TARDBP, forms aggregates in the motor cortex." (PMID 34548609, 2021). "TAR DNA-binding protein-43 (TDP-43) is known to accumulate in ubiquitinated inclusions of amyotrophic lateral sclerosis affected motor neurons, resulting in motor neuron degeneration, loss of motor functions, and eventually death." (PMID 34518579, 2021). "Cytoplasmic aggregation of the primarily nuclear TAR DNA-binding protein 43 (TDP-43) affects neurons in most amyotrophic lateral sclerosis (ALS) and approximately half of frontotemporal lobar degeneration (FTLD) cases." (PMID 34452489, 2021). "Neuronal cytoplasmic inclusions of the nuclear TAR DNA-binding protein 43 (TDP-43) is a characteristic of the neurodegenerative diseases amyotrophic lateral sclerosis and frontotemporal dementia." (PMID 34944052, 2021). "In a Drosophila model of amyotrophic lateral sclerosis (ALS) based on TDP-43 (TAR DNA-binding protein 43), activation of PPARγ was found to generate neuroprotective benefits." (PMID 34944727, 2021). "Aggregates of TAR DNA-binding protein (TDP-43) are a hallmark of several neurodegenerative disorders, including amyotrophic lateral sclerosis (ALS)." (PMID 33917983, 2021). "The accumulation of intracellular protein aggregates, such as tau in Alzheimer’s disease (AD), α-synuclein in Parkinson’s disease (PD), and TAR DNA-binding protein 43 (TDP-43) in amyotrophic lateral sclerosis (ALS) is the main pathological hallmark of several neurodegenerative diseases." (PMID 35069211, 2021). "TAR DNA‐binding protein 43 (TDP‐43) has been implicated in frontotemporal lobar degeneration with ubiquitin‐positive inclusions (FTLD‐TDP) and amyotrophic lateral sclerosis." (PMID 32449313, 2020). "Neuronal cytoplasmic inclusions containing TAR DNA-binding protein 43 (TDP-43) are a neuropathological feature of several neurodegenerative diseases, including amyotrophic lateral sclerosis (ALS), frontotemporal dementia (FTD), and Alzheimer’s Disease (AD)." (PMID 32979923, 2020).
amyotrophic lateral sclerosis (continued). "Intriguingly, it was demonstrated that TAR DNA-binding protein 43 (TDP-43) physically associates with mature miR-1 and miR-206 in individuals with amyotrophic lateral sclerosis." (PMID 33330108, 2020). "TAR DNA-binding protein 43 (TDP-43) is a 414-residue long nuclear protein whose deposition into intraneuronal insoluble inclusions has been associated with the onset of amyotrophic lateral sclerosis (ALS) and other diseases." (PMID 32872449, 2020). "TAR DNA-binding protein 43 (TDP-43; also known as TARDBP) is an RNA-binding protein whose aggregation is a hallmark of the neurodegenerative disorders amyotrophic lateral sclerosis and frontotemporal dementia." (PMID 32989039, 2020). "The results suggest that neuronal NF-κB signaling constitutes a novel therapeutic target for amyotrophic lateral sclerosis and related disorders with Tar DNA-binding protein 43 proteinopathy." (PMID 32457070, 2020). "Exosomes isolated from the brain of patients with Amyotrophic lateral sclerosis (ALS) contain TAR DNA-binding protein 43 (TDP-43), a major pathological protein in the disorder." (PMID 33255332, 2020). "Mutations or deregulation of transactive response DNA binding protein 43 (TDP43 or TARDBP) expression have been associated with a spectrum of neurodegenerative diseases including frontotemporal lobar degeneration (FTLD) and amyotrophic lateral sclerosis (ALS)." (PMID 32582692, 2020). "Numerous patient mutations in TARDBP, the gene encoding TDP-43, combined with data from animal and cell-based models, imply that altered RNA regulation by TDP-43 causes Amyotrophic Lateral Sclerosis and Frontotemporal Dementia." (PMID 30357366, 2019). "Cytosolic accumulation of TAR DNA-binding protein 43 (TDP-43) is a major neuropathological feature of amyotrophic lateral sclerosis and frontotemporal lobar degeneration." (PMID 30836866, 2019). "Dysregulation of TAR DNA-binding protein 43 (TDP-43) is a hallmark feature of frontotemporal dementia (FTD) and amyotrophic lateral sclerosis (ALS), two fatal neurodegenerative diseases." (PMID 31068973, 2019). "Four genes linked to familial cases of amyotrophic lateral sclerosis were investigated for antisense transcription: SOD1, FUS, TARDBP, and UBQLN2." (PMID 30610612, 2019). "The second dataset individually depleted three RBPs implicated in amyotrophic lateral sclerosis: FUS, TAF15 and TARDBP." (PMID 31238884, 2019). "Conversely, TAR DNA-binding protein (TDP-43) pathology is seen in the majority of patients with semantic variant primary progressive aphasia (svPPA) and frontotemporal dementia with amyotrophic lateral sclerosis (FTD-ALS)." (PMID 30704514, 2019). "One of the experiments under study selected FUS, TAF15 and TARDBP (referred to as TDP43 in the reference), since they are known to be related to amyotrophic lateral sclerosis (ALS)." (PMID 31238884, 2019). "TARDBP encodes the TDP-43 protein, which forms cytoplasmic inclusions in patients with the most frequent form of frontotemporal dementia (FTD) and most forms of amyotrophic lateral sclerosis (ALS) and in 60% of patients with AD." (PMID 30147999, 2018). "The RNA-binding and -processing protein TAR DNA-binding protein 43 (TDP-43) is heavily linked to the underlying causes and pathology of neurodegenerative diseases such as amyotrophic lateral sclerosis and frontotemporal lobar degeneration." (PMID 28510586, 2017). "Such promotion of in vitro pathology via CTraS was also confirmed in familial amyotrophic lateral sclerosis (ALS) models carrying TARDBP mutations; the neurite swellings and the reduction of cell viability were reproduced with a shorter culture period by CTraS induction." (PMID 29107593, 2017). "TAR DNA-binding protein 43 (TDP-43) is a main constituent of cytoplasmic aggregates in neuronal and glial cells in cases of amyotrophic lateral sclerosis and frontotemporal lobar degeneration." (PMID 28599005, 2017).